CD4 (CD4 molecule)
Diseases named in the same sentence as CD4 in open-access papers (continued):
Sharing a sentence is not in itself a finding about the gene and the disease.
Opportunistic infection (continued). "Given that CD4 cell count decreases in the presence of an opportunistic infection, HCV infection may be expected to affect CD4 cell decline in HIV positive individuals, given that HCV infection acts as an opportunistic infection in HIV positive individuals." (PMID 26225723, 2015). "Overall, the conclusion of the analysis showing the cost-effectiveness of DTG is robust to changes in most parameters (immunovirologic efficacy, utilities by CD4+ cell count level, discount rate, length of opportunistic infection, lack of emergence of resistance amongst others)." (PMID 26714188, 2015). "However, an increasing risk in anemia with decreasing values of CD4 cell count was seen at 12 months; and the observed association between anemia and lower CD4 cell count at 12 month might be related to poor immunological recovery and high viral load rather than to opportunistic infections." (PMID 26045966, 2015). "It has been shown previously that BDG levels were markedly higher (mean 142 pg/mL) in a HIV infected cohort with lower median CD4 counts (26, IQR 10–53, all without opportunistic infections), when compared to the cohort studied here (with a median CD4 count >600 pg/mL)." (PMID 27917362, 2015). "Furthermore, CD4+ T cell testing remains important for immunological and opportunistic infection management of patients with and without ART." (PMID 26720601, 2015). "We do not have information on CD4+ count, opportunistic infections, diarrheal disease, ART regimen, timing of ART, ART/CPT drug compliance, and drug adverse effects; these factors may positively/negatively affect TB treatment outcomes." (PMID 25478222, 2014). "HAART is initiated regardless of the patient’s history of opportunistic infection or CD4 count." (PMID 24252328, 2013). "The white blood cell count, absolute neutrophil count, absolute CD4+ cell count, and level of alkaline phosphatase were significantly higher among those with active opportunistic infection compared with those without active opportunistic infection." (PMID 24086734, 2013). "Case reports suggested that recombinant IL-2 administration could raise CD4+ T cell counts in ICL patients and help improve the clinical outcome of opportunistic infections, including cryptococcal meningitis, chronic mycobacterial disease, and relapsing herpes zoster infection." (PMID 23383227, 2013). "In this initial study, the only patient who did not normalize CXCR4 expression levels also failed to increase CD4+ T cell counts after IL-2 treatment and did not benefit clinically from the therapy, with continued occurrence of multiple opportunistic infections." (PMID 23383227, 2013). "In addition, about 60% of patients who were non-adherent and had low CD4 T cell count also suffered from different opportunistic infections." (PMID 23825577, 2013). "MRCP may be an alternative for patients with high CD4 counts that are receiving HAART therapy as they do not require biopsy specimens to test for opportunistic infections." (PMID 21994858, 2011). "The use of cotrimoxazole prophylaxis to prevent some opportunistic infections may have contributed to the high false negative rate, despite the low CD4 counts." (PMID 21589912, 2011). "For instance, the observed impact on IFN-γ production of ATG induction and CD4+ and CD8+ T-cell counts would suggest that low responses may ultimately act as a surrogate for the presence of lymphocytopenia, which constitutes a well-established biomarker for opportunistic infection." (PMID 39539802, 2024). "The CD4 count of the ART group was 20% higher (400 cells/mm3) than that of the ART-naïve group (331 cells/mm3), suggesting that the weakened immunity among the untreated individuals may result in HIV-related opportunistic infections, as well as cardiovascular complications." (PMID 38917149, 2024).
Opportunistic infection (continued). "However, cotrimoxazole resistance was higher among PLHIV than among people, which could be the result of cotrimoxazole prophylaxis provided to PLHIV for treatment of opportunistic infections, and cotrimoxazole prophylaxis is given to HIV-infected adults with a CD4 count of <500 cells/μl in Nepal." (PMID 35070354, 2022). "Arguably, the role of CD4 count in the current era of HIV monitoring is still crucial, particularly for patients presenting late to care as they are at high risk of presenting with opportunistic infections and also in areas where viral load testing is not affordable." (PMID 32228483, 2020). "PLHIV with an opportunistic infection may be initiated on ART regardless of CD4 count." (PMID 26039733, 2015). "A lack of CD4+ T-cell counts prior to the initiation of cART was observed in 1 of 10 patients and was probably related to clinical decisions not to request this testing if the patient had a concomitant opportunistic infection at the time of cART initiation or during hospitalization." (PMID 24789106, 2014). "Unlike their infected partners who received CD4 cell count testing and drugs to prevent opportunistic infections at the study clinic, the uninfected partners may have experienced limited direct benefits from study participation, and consequently may have been less motivated to attend visits." (PMID 22937017, 2012). "Although data from IDI indicate that short-term outcomes--CD4 cell count, incidence of opportunistic infections and self-reported adherence--do not differ between patients attending regular care and those attending the pharmacy refill program, outcomes may have been different for PF, NF and PWF." (PMID 19845963, 2009). "Even though ART initiation is no longer contingent upon CD4 counts, CD4 monitoring remains necessary for disease staging, defining advanced HIV (CD4 < 200), guiding prophylaxis with respect to opportunistic infections, and prognostication." (PMID 41374357, 2025). "This study has identified four risk factors of severe COVID-19 infection in PLHIV, namely having any comorbidity, a recent absolute CD4 count of < 200 cells/mm3, not being on ART, and having an active opportunistic infection." (PMID 36192742, 2022). "Reduction in CD4+ T cells and expansion of CD8+ T cells with a senescence phenotype have been found that alter the CD4:CD8 ratio but without the common presentation of T cell alterations such as viral and fungal opportunistic infections." (PMID 36004955, 2022). "We did not observe statistically significant differences in CD4 recovery depending on gender, HCV/HBV coinfections, comorbidities and opportunistic infections." (PMID 36298842, 2022). "In this regard, the prophylaxis for Pneumocystis jiroveci and other opportunistic infections should be administrated in PLWH with cancer when initiating treatment, regardless of CD4+ T-cell count." (PMID 32111093, 2020). "Furthermore, viral load, which may be a better indicator of immune competence than CD4 count was not measured: it has been shown that effective viral suppression reduces the incidence of opportunistic infections and a similar effect might be expected for clinical malaria." (PMID 27417903, 2016). "On the other hand, the history of opportunistic infections such as CMV, EBV, Mycoplasma, and Chlamydia, in absence of HIV and malignancies, is the consequence of the idiopathic CD4 lymphocytopenia." (PMID 26491451, 2015). "Persistently high peripheral levels of CD56+ NK cells were observed in a peculiar hemophiliac HIV/HCV co-infected patient with low CD4 counts, almost undetectable HIV viral load and no opportunistic infections." (PMID 23351719, 2013). "Despite very low CD4+ T cell counts, the special long-term HIV/HCV co-infected hemophiliac patient that we describe here is healthy and presents neither opportunistic infections nor any sign of virus-related cancer." (PMID 23351719, 2013).
Opportunistic infection (continued). "Indeed, this patient had several atypical clinical and radiologic characteristics.The patient’s CD4 T-cell count was higher than usual in the presence of this opportunistic infection and could be explained by a qualitative rather than quantitative immunodeficiency." (PMID 22802889, 2012). "No patient merited exclusion due to a low level CD4+ T-cell count and to the need to initiate ARV therapy; no patient had a diagnosis of opportunistic infections." (PMID 23101545, 2012). "Importantly, none of the three patients experienced severe opportunistic infections, neurotoxicity, or grade 3 and above cytokine release syndrome (CRS), indicating that the CD4 CAR-T cells were well tolerated in these patients." (PMID 41295262, 2025). "Opportunistic infection, Duration of first-line ART, Baseline CD4 count, Health facility where first-line ART started, Opportunistic infection after ART initiated, and Nonreversible transcriptase inhibitors based ART regimen were independent determinants of First-line ART treatment failure." (PMID 33175902, 2020). "The slightly lowered CD4 T-cell counts, combined with a reduced T-cell CD4:CD8 ratio, could not explain this opportunistic infection either, and therefore we embarked on functional assays to test the T-helper functions." (PMID 26877197, 2016). "This also emphasizes that even in the era of expanded ART eligibility for patients with CD4 < 350 (as were the guidelines at the time these patients were in treatment), many patients were still not accessing ART early enough to prevent opportunistic infections and improve survival." (PMID 25993636, 2015). "Nevertheless, CD4 cell counts are not included in the criteria for INSHI’s case definitions, as the number of CD4 cells measured in the periphery does not reflect the function and number of CD4 cells at the site of an opportunistic infection." (PMID 24354779, 2013). "Two-thirds of the respondent’s CD4 level is between 200 and 1000, 74% not perceived stigma, 74.9% have moderate-Strong social support, 70.1% lived with HIV between 1 and 3 years, 80.2% did not have an opportunistic infection, 84.9% were in HIV Stage II, and 69.5% does not use substances." (PMID 37029371, 2023).
melanoma (1,186 papers, 2001 to 2026). A malignant, usually aggressive tumor composed of atypical, neoplastic melanocytes. "In large human transcriptomic and sequencing datasets, a role for CD4+ T cells in enhancing immune checkpoint blocker-mediated responses in persons with melanoma and mismatch-repair-deficient colon cancers that have downregulated MHC class I was suggested." (PMID 41876718, 2026). "Its expression is often associated with increased infiltration of FOXP3+ CD4+ Tregs, which promote immunosuppressive tumor microenvironments and predict unfavorable outcomes in melanoma." (PMID 40725830, 2025). "In another study, CD4+ T cells in primary biopsies of stage II melanoma were associated with favorable clinical outcomes." (PMID 39825956, 2025). "Our data reinforce this evidence, demonstrating that the lactate‐rich environment associated with male melanoma improves CD4+ T‐cell recruitment and Treg‐polarisation, and that this is effectively prevented by LDH‐A impairment." (PMID 39888245, 2025). "The presence of IL-4 enhances tumor metastasis and the highly metastatic variant of B16 melanoma (B16F10) induces a distinct CD4 T cell subset capable of strong IL-4 production compared with T cells induced by the low metastatic variant (B16F1)." (PMID 39452870, 2024). "A study on T-cell characteristics associated with irAEs in patients with melanoma reported that activated CD4 memory T-cell abundance and T-cell receptor diversity at baseline correlated with severe irAE development." (PMID 38183211, 2024). "We also reveal evidence for CEACAM1 expression on CD4+ T cells that are phenotypically consistent with FoxP3+ regulatory T cells whose presence correlates with the melanoma-associated TME using multiple approaches." (PMID 38956268, 2024). "When we analyzed infiltrating lymphocytes in melanoma tumors from these mice, we observed higher numbers of CD4+ and CD8+ cells in mice that received Opn-deficient Tregs compared with wild-type controls." (PMID 39272810, 2024). "Transfer learning through the CDAN framework effectively captured the immunogenic features of melanoma-associated CD4+ T cell neoepitopes." (PMID 38920343, 2024). "Preclinical studies demonstrated that anti-CTLA-4 treatment was associated with the expansion of IFNγ+ICOS+CD4+ T cells in melanoma and other solid tumors." (PMID 39247203, 2024). "A following up study aiming to analyze the effect of DTIC+Tα1+low dose IFN-α in treating melanoma patients demonstrated response rate of 50%, associated with increase in CD4+ T cells and NK cell numbers in the peripheral blood." (PMID 37529610, 2023). "In this scenario, CD4+ T cells play on-target cytotoxicity of melanoma while neutrophils are responsible for killing antigen loss variants." (PMID 38037114, 2023). "We therefore investigated the ability of TRP-1 CD4+ T cells to control MHC-II-deficient tumour cells by disrupting the Ciita gene encoding the MHC-II transactivator in HCmel12 mouse melanoma cells using CRISPR–Cas9 gene editing." (PMID 37316667, 2023). "High TMB associated with HLA class II positive melanoma and the ability of neoantigens generating CD4+ and CD8+ TILs are the two major factors leading to the results." (PMID 36646683, 2023). "Although previous studies claimed that tumor-associated antigens do not induce an effective cytotoxic T cell response and tumor-specific CD4+ T lymphocytes, our present data suggest that tumor-associated antigens have a predominant role in advanced melanoma." (PMID 37680638, 2023). "A log-rank test was performed for 69 metastatic melanoma patients (the whole cohort of melanoma patients) to investigate the association between the frequencies of peripheral CD4+CD26+ T cells and the OS." (PMID 37170241, 2023). "Our study firstly demonstrates that peripheral blood circulating CD4+CD26high T lymphocytes represent potential biomarkers whose perturbations are associated with reduced survival and worse clinical outcomes in melanoma patients." (PMID 37170241, 2023).
melanoma (continued). "Another melanoma-associated antigen, gp100, is presented by tumor cells to CD4+ T cells in a manner dependent on gp100’s transmembrane domain." (PMID 36512410, 2023). "In analyzing the clinical trial results, ex vivo ELISPOT assays were performed to detect IFNγ-producing CD8 and CD4 T-cell responses specific to the DC vaccine loaded melanoma-associated antigens Tyrosinase, MART-1 and MAGE-A6." (PMID 37938561, 2023). "In human melanoma, infiltration of NeoAg-specific CD4+ T cells is associated with antitumor effector phenotypes of macrophages, B cells and CD8+ T cells." (PMID 37400675, 2023). "CANX (calnexin) has been associated in melanoma with an enhancement in the expression of PD-1 on CD4+ and CD8+ T cells, but also with a promotion of tumor growth and an inhibition of T cell infiltration." (PMID 37686682, 2023). "They suggest that female melanoma patients have a statistically significantly higher frequency of tumor-associated, antigen-specific CD4+ T-cells than their male counterparts." (PMID 35053577, 2022). "We observed that CD80 blockade caused CD4 Teff accumulation in melanoma TILs and a concomitant decrease in dLNs, suggesting lymphatic migration was inhibited by blockade of CD80/PD-L1." (PMID 35449134, 2022). "A recent study on T cell characteristics with severe irAEs (defined as grade 3 and higher) revealed that the abundance of activated peripheral CD4+ memory T cells before ICIs was associated with the development of severe irAEs in melanoma patients." (PMID 36261600, 2022). "The administration of autologous activated pDCs loaded with tumor-associated peptides to melanoma patients has been shown to induce specific CD4+ and CD8+ T cells responses." (PMID 36230990, 2022). "After using these constructs to treat pre-established melanomas in animal models, remission was observed, which is associated with the ability of mouse lymphoid cells to mount a tumor-specific CD4+ interleukin (IL)-17 dependent response." (PMID 35495634, 2022). "It has been reported in this regard that a higher Foxp3+ CD4+ regulatory T cell level at baseline is significantly associated with favorable outcomes with ipilimumab therapy in patients with melanoma." (PMID 36237314, 2022). "A recent study demonstrated that the peripheral CD4 + T-cell subset is important for new tumor protection and is associated with a favorable response to immunotherapy in melanoma patients." (PMID 36057637, 2022). "In non–small cell lung cancer (NSCLC), malignant pleural mesothelioma and melanoma, EM-like CD4 T cells and/or CD8 TEMRA at baseline were associated with response to ICI." (PMID 36388466, 2022). "For this purpose, we depleted CD4+ T cells from Asm-deficient and Asm-WT mice and transplanted B16-F1 melanoma cells." (PMID 36426850, 2022). "In the last decade, growing evidence has indicated that CD4+ T cells can contribute to control tumor growth in humans, and CD4+ T cells specific for neo-antigens have been detected within tumors with elevated Tumor Mutational Burden, such as melanoma." (PMID 36385379, 2022). "One of the main failures associated with melanoma immunotherapy is reduced stimulation of both CD4+ and CD8+ T cells, leading to incomplete tumor clearance and immunological memory." (PMID 35162988, 2022). "Pre-treatment PD-L1 expression on peripheral CD8+ and CD4+ T-cells was associated with worse outcome in melanoma patients receiving CTLA-4 blockade." (PMID 34071888, 2021). "In anti-CTLA4-treated patients of melanoma, several studies showed that a reduction in the frequency of naive-phenotype CD4+ or CD8+ T cells were associated with better OS in the blood." (PMID 34446007, 2021). "Quezada and colleagues reported the presence of cytotoxic CD4 T cells and their importance to eradicate tumors in lymphopenic mice with melanoma, particularly in association with CTLA-4 blockade." (PMID 34064410, 2021).